MIR600HG (MIR600 host gene)
Synonyms: GL012; FLJ22161; C9orf45; NCRNA00287
Gene: Long non-coding RNA gene on chromosome 9 (123,109,494 to 123,115,477, reverse strand). Ensembl gene ENSG00000236901.
Diseases named in the same sentence as MIR600HG in open-access papers:
MIR600HG is named in the same sentence as 11 diseases in open-access papers, as found by Europe PMC text mining. Sharing a sentence is not in itself a finding about the gene and the disease. The quoted sentences say what the papers report.
colorectal cancer (2 papers, 2022). A primary or metastatic malignant neoplasm that affects the colon or rectum. "Overexpression of MIR600HG inhibits tumor invasion and enhances chemotherapy sensitivity, providing a new strategy for colorectal cancer treatment." (PMID 35280739, 2022). "Pieces of the literature suggested that MIR600HG suppressed metastasis and development by targeting oncogenic ALDH1A3 in colorectal cancer." (PMID 36186449, 2022).
autism (1 paper, 2023). Persistent deficits in social interaction and communication and interaction as well as a markedly restricted repertoire of activity and interest as well as repetitive patterns of behavior. "Also, we highlighted that MIR600HG interacts with multiple mRNAs through autism-susceptible miRNAs (for example, hsa-miR-106a/b-5p, hsa-miR-107, hsa-miR-92a-3p, hsa-miR-15b-5p, hsa-miR-21-5p, and hsa-miR-148b-3p)." (PMID 38057311, 2023).
oropharyngeal squamous cell carcinoma (1 paper, 2023). "In oropharyngeal squamous cell carcinoma, MIR600HG affects the occurrence and development of tumors through autophagy-related pathways." (PMID 37741887, 2023).
pancreatic cancer (1 paper, 2023). "First, the functions of MIR600HG, hsa-miR-342-3p and ANLN in pancreatic cancer require further experimental research." (PMID 37741887, 2023).
pancreatic ductal adenocarcinoma (1 paper, 2023). An infiltrating adenocarcinoma that arises from the epithelial cells of the pancreas. "MIR600HG is a prognostic target of pancreatic ductal adenocarcinoma prediction, and suppresses metastasis in colorectal cancer." (PMID 37081063, 2023).
tumor (6 papers, 2020 to 2022). "MIR600HG was observed to inhibit stemness, metastasis and oxaliplatin resistance in CRC by targeting ALDH1A3, and overexpression of MIR600HG combined with oxaliplatin treatment was found to inhibit tumor recurrence." (PMID 35155247, 2022). "A few studies have demonstrated the function of MIR600HG, which is considered a lncRNA biomarker for predicting the progression of tumor patients." (PMID 36204312, 2022). "MIR600HG is a tumor suppressor in the family of lncRNAs with a protective role in various malignancies." (PMID 34760926, 2021).
cancer (2 papers, 2020 to 2021). A tumor composed of atypical neoplastic, often pleomorphic cells that invade other tissues. "LncRNA MIR600HG was a significant prognostic factor in many cancers such as PAAD and PRA, among which MIR600HG was a low risk factor in PAAD." (PMID 34195204, 2021).
MIR600HG also shares sentences with these, for which no sentence is quoted: bladder cancer (1 paper); cholangiocarcinoma (1); colorectal (1); gastric cancer (1).